Y_RNA (Y RNA )
Gene: Miscellaneous RNA gene on chromosome 6 (85,777,639 to 85,777,755, reverse strand). Ensembl gene ENSG00000200427.
Homologues: Orthologues: chimpanzee Y_RNA (99% identical). Paralogues in human: Y_RNA (74% identical), RNY1 (72% identical), Y_RNA (71% identical), Y_RNA (70% identical), Y_RNA (69% identical), RNY1P11 (68% identical), Y_RNA (68% identical), RNY1P8 (67% identical), Y_RNA (67% identical), Y_RNA (66% identical), RNY1P12 (65% identical), Y_RNA (65% identical), and 85 more.